PAPPA-AS1 (PAPPA antisense RNA 1)
Synonyms: DIPAS; PAPPAS; PAPPA-AS; TAF4B; TAF2C2; TAFII105; NCRNA00156; PAPPAAS
Gene: Long non-coding RNA gene on chromosome 9 (116,398,157 to 116,400,606, reverse strand). Ensembl gene ENSG00000256040.
Subcellular location: Endoplasmic reticulum membrane
Diseases named in the same sentence as PAPPA-AS1 in open-access papers:
PAPPA-AS1 is named in the same sentence as 6 diseases in open-access papers, as found by Europe PMC text mining. Sharing a sentence is not in itself a finding about the gene and the disease.
PAPPA-AS1 shares sentences with these, for which no sentence is quoted: Bladder cancer (1 paper); cervical cancer (1); colorectal cancer (1); esophageal cancer (1); esophageal squamous cell carcinoma (1); prostate carcinoma (1).